ADCY2 (adenylate cyclase 2)
Diseases named in the same sentence as ADCY2 in open-access papers:
ADCY2 is named in the same sentence as 58 diseases in open-access papers, as found by Europe PMC text mining. Sharing a sentence is not in itself a finding about the gene and the disease. The quoted sentences say what the papers report.
bipolar disorder (5 papers, 2016 to 2025). A disorder of the brain that causes unusual shifts in mood, energy, activity levels and the ability to carry out day-to-day tasks. "The single nucleotide polymorphism rs13166360, causing a substitution of valine (Val) 147 to leucine (Leu) in the adenylyl cyclase 2 (ADCY2), has previously been associated with bipolar disorder (BD)." (PMID 39003412, 2025). "ADCY2 is known to associate with bipolar disorder and severe chronic obstructive pulmonary disease." (PMID 34993155, 2021). "Genes within these clusters including ADCY2 and AKAP have been associated with bipolar disorder and schizophrenia." (PMID 32000760, 2020).
glioma (5 papers, 2014 to 2024). A benign or malignant brain and spinal cord tumor that arises from glial cells (astrocytes, oligodendrocytes, ependymal cells). "Subsequent IHC staining revealed the expression of PDE8B, ABAT, and ADCY2 proteins in glioma WHO grades II-IV." (PMID 38989284, 2024). "The protein expression of PDE8B, ABAT, and ADCY2 decreased in glioma grade IV compared with glioma grades III and II." (PMID 38989284, 2024). "The expression of PDE8B, ABAT, and ADCY2 proteins decreased with increasing glioma WHO grade." (PMID 38989284, 2024). "ADCY2 (adenylate cyclase 2), which is involved in the calcium signaling pathway, may play a crucial role in the development and progression of gliomas." (PMID 35800363, 2022). "In addition, GRM1 and adenylate cyclase 2 (ADCY2) may contribute to glioma development through the calcium signaling pathway." (PMID 36980973, 2023). "Similar to the TCGA datasets, all 11 genes exhibited WHO grade-dependent expression in glioma samples, with 6 upregulated (LDHA, MIF, NAMPT, PGK1, SAT1, and PLOD2) and 5 downregulated genes (ALDOC, ABAT, ADCY2, GALNT13, and PDE8B)." (PMID 38989284, 2024). "The results revealed that high mRNA expression of ADCY1, ADCY2, and ADCY5 were statistically related to better OS in Glioma patients with P < 0.01, compared with the low expression groups respectively." (PMID 39319137, 2024). "Consistent with the changes in expression, patients with higher expression of LDHA, MIF, NAMPT, PGK1, SAT1, and PLOD2, and lower expression of ALDOC, ABAT, ADCY2, GALNT13, and PDE8B showed poorer survival rates in all glioma samples." (PMID 38989284, 2024).
colon cancer (4 papers, 2008 to 2022). "The adenylate cyclase ADCY2 is overexpressed in prostate and colon cancer metastases, and in pancreatic neuroendocrine tumors." (PMID 35631574, 2022). "LEC3 was up-regulated in MG-thymoma, but down-regulated in colon cancer, Similar to Adenylate cyclase (ADCY2, magnesium ion binding), and the iroquise homeobox gene IRX2, (transcription factor activity)." (PMID 18545673, 2008).
colorectal cancer (4 papers, 2013 to 2022). A primary or metastatic malignant neoplasm that affects the colon or rectum. "Another adenylate cyclase family member, ADCY2, was recently reported to be associated with altered survival in colorectal cancer." (PMID 24113161, 2013). "Aberrant methylation of ADCY2 is observed in oral cancer, colorectal cancer, prostate cancer, and urinary bladder cancer." (PMID 34993155, 2021). "In colorectal cancer, ADCY2 could also be an important prognostic marker." (PMID 34900686, 2021).
oral cancer (3 papers, 2020 to 2024). "The MiRNA target prediction showed functional molecular annotation including specific miRNA-targets hsa-miR-4282, hsa-miR-2052, hsa-miR-216a-3p, for CYP1B1, C7, and ADCY2 respectively associated with oral cancer." (PMID 32887903, 2020). "Based on genomic to phenomic investigations, we have found new genes including ADCY2, SERPINB5, and ANAPC13 linked with oral cancer that could be potential diagnostic or drug targets." (PMID 32887903, 2020).
asthma (2 papers, 2011 to 2025). "We found that ADCY2, PDE4B, DNAH5 and KIF3A were again associated with asthma (p<0.05) at the gene level." (PMID 21912604, 2011). "Furthermore, at least one previously associated SNP within ADCY2 and DNAH5 was associated with asthma." (PMID 21912604, 2011). "Our investigation revealed that six of these genes (PDE4B, SPRR2B, ADCY2, KIF3A, DNAH5, and PLAU) were located in chromosomal regions that had been previously linked to asthma or other allergic disease phenotypes and had been shown to be regulated during allergic inflammation." (PMID 21912604, 2011). "A genome‐wide interaction analysis of air pollution exposure and childhood asthma showed interactions with three genes, ADCY2, B4GALT5, and DLG2, which have been found to be important for the development of asthma." (PMID 40133993, 2025).
chronic obstructive pulmonary disease (2 papers, 2019 to 2021). A chronic and progressive lung disorder characterized by the loss of elasticity of the bronchial tree and the air sacs, destruction of the air sacs wall, thickening of the bronchial wall, and mucous accumulation in the bronchial tree. "In addition, single-nucleotide polymorphisms in ADCY2 have beenassociated with severe chronic obstructive pulmonary disease." (PMID 30985858, 2019).
dilated cardiomyopathy (2 papers, 2018 to 2021). Cardiomyopathy which is characterized by dilation and contractile dysfunction of the left and right ventricles. "The upregulated hub genes ADCY2, CXCL12, and GNB4 were enriched in calcium signal pathway, dilated cardiomyopathy, hypertrophic cardiomyopathy, neuroactive ligand-receptor interaction pathway, and vascular smooth muscle contraction pathways related to cardiomyopathy." (PMID 34603374, 2021).
epithelial ovarian cancer (2 papers, 2020 to 2022). "In addition to ADRB1, BRCA1-deficient ovarian cancer cells also express high levels of other factors related to catecholamine-adrenoceptor-cAMP pathway regulation, such as the adenylate cyclase ADCY2 and G protein-coupled receptor ADGRB1." (PMID 35517499, 2022).
head and neck squamous cell carcinoma (2 papers, 2021 to 2022). A squamous cell carcinoma that arises from any of the following anatomic sites: lip and oral cavity, nasal cavity, paranasal sinuses, pharynx, larynx, and salivary glands. "Though ADCY2 has been found to be a novel lipid prognostic feature in head and neck squamous cell carcinoma, it has not been studied in BCa." (PMID 36313639, 2022).
neuroblastoma (2 papers, 2013 to 2024). Neuroblastoma (NB) is the most common solid, extracranial childhood tumor. "In the hypoxanthine phosphoribosyl transferase (HPRT)‐deficient rat B103 neuroblastoma model of LNS, Adcy2 is almost completely absent, indicating a possibly important role of Adcy2 in LNS." (PMID 39073001, 2024).
Parkinson disease (2 papers, 2022 to 2024). A progressive degenerative disorder of the central nervous system characterized by loss of dopamine producing neurons in the substantia nigra and the presence of Lewy bodies in the substantia nigra and locus coeruleus. "A combined research approach using GWAS on Parkinson's disease patients and a Drosophila model of L-DOPA-induced dyskinesia (LID) reveals that LID is linked to ADCY2 signaling." (PMID 36008531, 2022).
prostate carcinoma (2 papers, 2021 to 2023). A carcinoma that arises from epithelial cells of the prostate gland. "Meanwhile, ADCY2 was predicted as a target of miR-182 in stem cells and prostate cancer, which was also observed in our analysis." (PMID 38174044, 2023).
Alzheimer disease (1 paper, 2024). A progressive, neurodegenerative disease characterized by loss of function and death of nerve cells in several areas of the brain leading to loss of cognitive function such as memory and language. "Although Adcy2 is associated with APP levels under acute stress conditions (see Alzheimer's Disease section), its role in stress remains largely unknown." (PMID 39073001, 2024).
Anxiety (1 paper, 2013). Intense feelings of nervousness, tension, or panic often arise in response to interpersonal stresses. "For instance, while Pdyn is the only gene positively correlated with anxiety-like behavior in XX mice, Htr1a, Cdk5, Adcy2, Akt1, Akt2, and Akt3 positively correlate with anxiety-like behavior in XY- mice." (PMID 24199867, 2013).
congenital heart disease (1 paper, 2024). A heart disease that is present at birth. "Moreover, ADCY2 mutations have been associated with congenital heart disease and abnormal calcium signaling." (PMID 38643935, 2024).
dementia (1 paper, 2024). Loss of intellectual abilities interfering with an individual's social and occupational functions. "As a risk factor for dementia, chronic stress may increase Adcy2 expression and cAMP signaling, leading to elevated APP levels and consequently Aβ accumulation." (PMID 39073001, 2024). "However, a direct association between Adcy2 and stress preceding dementia has not been established." (PMID 39073001, 2024).
embryonic carcinoma (1 paper, 2022). "In addition, it has been reported that P19 cells (embryonic carcinoma cells) up-regulate ADCY2 during neuronal and mesodermal differentiation, highlighting a possible role of ADCY2 in cell differentiation during development." (PMID 35307032, 2022).
gallstones (1 paper, 2022). Solid crystalline precipitates in the biliary tract, usually formed in the gallbladder, resulting in the condition of cholelithiasis. "Our study showed that the alteration of rs4072341 in adenylyl cyclase 2 (ADCY2) gene also reduced the occurrence of gallstones." (PMID 35651949, 2022). "These loci are located in seven different genes, including SLC4A5, MUC4, FTO, NPC1 and FXYD2 genes that may increase the risk of gallstone in the Tibetan population, while CFTR and ADCY2 genes that reduce the risk of gallstone in the Tibetan population." (PMID 35651949, 2022). "Therefore, we speculate that ADCY2 gene may be involved in adipocyte differentiation and thus affect the formation of gallstones." (PMID 35651949, 2022).
hypertriglyceridemia (1 paper, 2019). A laboratory test result indicating elevated triglyceride concentration in the blood. "In the case of IRS1 (cg21511036), AKT1S1 (cg03813033), ADCY2 (cg12566890 and EHMT2 (cg00210002) are hypomethylated, whereas AKT1 (cg01749142), FOXO3 (15283498), are hypermethylated in subjects with insulin resistance and hypertriglyceridemia." (PMID 30926763, 2019).
ischemic stroke (1 paper, 2024). A stroke disorder caused by obstruction of blood flow to the brain, due to thrombotic (local blood clot formation) or embolic (due to a blood clot or other material traveling from another site) event. "In a GWAS, a gene locus associated with factor VII‐activating protease (FSAP) activity (rs35510613) was identified 19 kb upstream of Adcy2 in ischemic stroke patients." (PMID 39073001, 2024). "Current studies on Adcy2 in stroke mainly come from ischemic stroke." (PMID 39073001, 2024).
major depressive disorder (1 paper, 2024). An episode of depression lasting two or more weeks without an intervening episode of mania. "Interestingly, Adcy2 is similarly dysregulated, among other retrograde endocannabinoid signaling pathway genes, in patients with major depressive disorder (MDD), although the directionality of gene expression is not stated in this study." (PMID 39073001, 2024).
mild cognitive impairment (1 paper, 2024). "Besides SNPs, decreased Adcy2 methylation is found in AD and mild cognitive impairment (MCI) patients compared to healthy controls, with the greatest effects observed in males." (PMID 39073001, 2024).
temporal lobe epilepsy (1 paper, 2024). A localization-related (focal) form of epilepsy characterized by recurrent seizures that arise from foci within the temporal lobe, most commonly from its mesial aspect. "Adcy2 mRNA is downregulated in the hippocampus of both individuals with temporal lobe epilepsy and mouse models of status epilepticus." (PMID 39073001, 2024). "Interestingly, a proteomics study reports upregulated hippocampal Cox2, an enzyme that stimulates Adcy2 activity, in a rat model of temporal lobe epilepsy." (PMID 39073001, 2024).
cancer (13 papers, 2013 to 2023). A tumor composed of atypical neoplastic, often pleomorphic cells that invade other tissues. "The association between ADCY2 and some immune checkpoints in pan-cancer was first explored, including those that promote immunotherapy and inhibit the efficacy of immunotherapy." (PMID 36313639, 2022). "In comparison to normal tissues, Nos2, Hgf, Lama1, Csf3r, Csf2rb2, Col4a1, Col4a2, Adcy2, Adcy4, Gstm3 and Gstm6 were identified as the most significant genes in cancer pathways." (PMID 37774039, 2023). "ADCY2 was found to be associated with most cytokines and presented a tumor immune microenvironment dominated by MHC and chemokine in most cancer types." (PMID 36313639, 2022). "Aberrant methylation of ADCY2 is observed in many other cancers." (PMID 35800363, 2022). "However, in the pan-cancer analysis, we found that the expression level of ADCY2 in tumor tissues was lower than that in normal tissues, which may be due to hypermethylation." (PMID 36313639, 2022). "Both the ADCY2 and SUGCT genes are involved in cellular metabolism and are reported to be altered in cancer." (PMID 38137002, 2023). "By contrast, ADCY1 expression did not affect the prognosis of AML patients, suggesting the actions of group 2 adenylyl cyclases (ADCY2, ADCY4 and ADCY7) in AML differ from those in other cancers." (PMID 32568101, 2020). "More biological investigation should be conducted in future to validate the correlation of three potential miR-146a-5p targets (PRKACB, ADCY2, and ADCY5) and miR-146a-5p in cancers." (PMID 31285693, 2019). "It appears that the interactomes of five out of the 17 lithium-sensitive genes (ADCY2, ADCY5, ADCY7, BPNT1, and HIPK3) do not show significant mutual enrichment with the cancer pathways explored in this study." (PMID 31114752, 2019).
tumor (12 papers, 2011 to 2025). "The high score of the ADCY2high group suggested a high expression of ADCY2 associated with tumor heterogeneity, indicating a worse immunotherapy effect and prognosis for BCa patients." (PMID 36313639, 2022). "While 15 genes were found to be altered in two or more tumors, only 5 mutations occurred in more than one tumor model (ADCY2 p.V147L, ERBB2 p.I655V, NCF2 p.H308Q, SYNE1 p.L885V, and ZNF814 p.158V)." (PMID 26270481, 2015). "Moreover, increased ADCY2 expression is associated with worse prognosis, higher tumor heterogeneity, and worse immunotherapy effect." (PMID 36313639, 2022). "This study revealed that increased expression of ADCY2 was significantly correlated with increased tumor heterogeneity, predicting worse survival and immunotherapy response in BCa patients." (PMID 36313639, 2022). "A higher level of ADCY2 was shown to connect to longer OS in our study, but few studies reported on its role in tumor progression." (PMID 32789468, 2020). "GABA receptor signaling pathway enrichment was defined by elevated expression of GABRB3 and potassium channel genes, KCNN1, KCNN2, and KCNQ3, and decreased expression of ADCY2, which have all been indicated as important in tumor growth (32, –, 34)." (PMID 28049147, 2017). "In the present study, we identified elevated levels of ADCY2 and PRKAR1A transcripts in a database of SI NETs compared to normal SI mucosa, suggesting that cAMP signaling may indeed be activated in tumor cells." (PMID 21853033, 2011).
neurodegenerative disease (2 papers, 2013 to 2024). A disorder of the central nervous system characterized by gradual and progressive loss of neural tissue and neurologic function. "Adcy2 has also been reported as an NAD‐binding protein, a family of proteins associated with multiple neurodegenerative disease‐related pathways." (PMID 39073001, 2024).
psychiatric disorder (2 papers, 2024 to 2025). A disorder characterized by behavioral and/or psychological abnormalities, often accompanied by physical symptoms. "Mutations and expression changes of adenylyl cyclase 2 (Adcy2), a CNS‐enriched enzyme that converts ATP to cAMP, are associated with several neurodegenerative and psychiatric disorders." (PMID 39073001, 2024). "In the CNS, dysfunction of Adcy2 is observed in multiple neurological diseases, including neurodegenerative disorders, psychiatric diseases, and other neurological conditions." (PMID 39073001, 2024). "It seems that changes in Adcy2 expression levels are predominantly found in neurodegenerative disorders, whereas Adcy2 SNPs are more common in psychiatric diseases." (PMID 39073001, 2024). "Next, we describe recent findings on the roles of Adcy2 in neurodegenerative disorders, psychiatric diseases, and other neurological conditions." (PMID 39073001, 2024). "These ADCY2-specific findings contribute to a growing number of human and mouse studies collectively pointing towards a prominent role of cAMP-related signaling pathways in psychiatric disorders including BD." (PMID 39003412, 2025).
cardiovascular disease (1 paper, 2025). "Comparative transcriptomic analysis revealed that genes related to cardiovascular disease (e.g., Sgcb, Adcy2, Itga1, Itgb8, Ifng, and Gpc1) were upregulated in the livers of R. pruinosus compared to carnivorous and omnivorous rodents, indicating a higher cardiovascular disease risk." (PMID 40941321, 2025).
neurological disorders (1 paper, 2024). "Abnormal Adcy2 expression and mutations have been reported in various neurological disorders in both rodents and humans." (PMID 39073001, 2024). "First, it remains unclear whether Adcy2 alteration or its SNPs identified in neurological disorders is causative or secondary to other changes." (PMID 39073001, 2024). "Although significant progress has been made in identifying Adcy2's involvement in neurological diseases, several key questions remain unanswered." (PMID 39073001, 2024). "Developing these genetic tools will enable in‐depth functional studies and shed light on the significance of Adcy2 in neurological disorders." (PMID 39073001, 2024). "In this review, we summarize recent findings on Adcy2 expression and function in neurological diseases." (PMID 39073001, 2024). "Answers to these questions will enable a comprehensive understanding of the expression and function of Adcy2 in neurological diseases, which will substantially move the field forward." (PMID 39073001, 2024). "In this review, we focus on the functions of Adcy2 in various neurological diseases, with the hope of stimulating interest and promoting further research in this field." (PMID 39073001, 2024). "Second, what is the function of Adcy2 in the pathogenesis of each neurological disorder?" (PMID 39073001, 2024).
ADCY2 also shares sentences with these, for which no sentence is quoted: infection (6 papers); viral infection (4); bladder cancer (2); childhood asthma (2); cyst (2); diabetes (2); schizophrenia (2); allergic disease (1); brain tumors (1); brucellosis (1); cardiomyopathy (1); clear cell renal cell carcinoma (1); congestive heart failure (1); epilepsy (1); hypertrophic cardiomyopathy (1); Insulin resistance (1); Lesch-Nyhan syndrome (1); lung carcinoma (1); metabolic syndrome (1); mucoepidermoid carcinoma (1); neurodevelopmental disorder (1); ovarian cancer (1); pancreatic neuroendocrine tumor (1); pneumococcal infection (1); sarcoma (1); Stroke (1); Tourette syndrome (1); type 1 diabetes mellitus (1).